BCL2 (BCL2 apoptosis regulator)
Diseases named in the same sentence as BCL2 in open-access papers (continued):
Sharing a sentence is not in itself a finding about the gene and the disease.
tumor (continued). "The relative tumor burdens present within brains harvested at this 3-week time point are consistent with the noninvasive imaging results, with visibly smaller tumors present in mice that received Bcl-2-expressing NSCs." (PMID 30026762, 2018). "In fact, it has been observed that overexpression of Bcl-2 or down-regulation of Bax can inhibit many tumor cell apoptosis, while down regulation of Bcl-2 or up-regulation of Bax can increase the apoptosis rate of tumor cells." (PMID 30111807, 2018). "The Δ% values of ADC and D were highly positively correlated with the Δ% values of Ki-67 and CA125, moderately positively correlated with the Δ% values of tumor size and Bcl-2, and moderately negatively correlated with the Δ% values of apoptosis and tumor necrosis." (PMID 30518386, 2018). "Bak is a gene that promotes tumor cell apoptosis and belongs to the Bcl-2 gene family." (PMID 29679278, 2018). "Importantly, S55746 induces the critical hallmarks of the mitochondrial apoptosis pathway and kills BCL-2 dependent tumor cells in a BAX/BAK dependent manner." (PMID 29732004, 2018). "However, our current TMA study indicated that the higher expression of ANXA7 also included the upregulation of tumor proliferation markers such as Bcl-2 and CD-10." (PMID 30321230, 2018). "DTX achieves its anti-tumour effect by disrupting microtubule dynamics and inducing G2/M cell cycle arrest, which promotes apoptosis through the phosphorylation of antiapoptotic protein Bcl-2." (PMID 30419852, 2018). "This illustrates that the chemotherapeutic agents which could induce c-Bax expression could be applied to Bcl-2-driven tumor cells and patients." (PMID 30013101, 2018). "Our study demonstrates that m-TRβ1 expression in SK-hep1 cells decreases cancer cell proliferation, impedes tumor cell migration, and inhibits tumor growth in vivo by up-regulating Caspase-3, 4-1BB, and Bak expression, increasing Caspase-3 activity, and down-regulating Bcl-2 expression." (PMID 29679278, 2018). "Finally, even if a small fraction of injected CD-NSCs maintains coexpression of v-myc and Bcl-2, they would quickly succumb to the antiproliferative chemotherapeutics generated upon administering prodrug intended for the dividing tumor cells." (PMID 30026762, 2018). "The results in vivo also confirmed that knockdown of NEAT1 sensitized the OS cells to DPP-induced tumor regression, delayed the tumor growth with reduced levels of Ki-67, BCL-2, and cyclin D1 signals, suggesting that NEAT1 is an oncogene and chemotherapy resistant factor in OS." (PMID 29654165, 2018). "It was reported that CRC patients above the age of 50 showed decreased Bax/Bcl‐2 ratios that might differentially control tumor cell apoptosis between the various age groups of patients." (PMID 28345223, 2017). "BCL2 itself seems to act as both an oncogene and a tumor suppressor gene in different tumor types." (PMID 28396899, 2017). "The treatment with C_BCNU@HCLI had a net effect on the expression of bcl-2, decreasing in a significant manner this anti-apoptotic factor in the tumour tissue by comparison to all the other types of treatments and thus reducing the survival chance of the tumour cells." (PMID 29156646, 2017). "Thus, the cytotoxic effects of DOX on tumors are enhanced by promoting tumor cell apoptosis through a Bcl-2/caspase-mediated apoptosis signaling pathway." (PMID 28938559, 2017). "Continuous IHC nuclear score for BRCA1 correlated positively with CK5/6 (r = 0.24, p<0.0001), basal nature of the tumor (r = 0.52, p<0.0001), bcl2 (r = 0.13, p = 0.04), and AR nuclear (r = 0.33, p<0.0001) scores and negatively with age (r = -0.14, p = 0.048) and tumor grade (r = -0.25, p = 0.01)." (PMID 28863181, 2017). "As Bcl-2 is involved in conferring resistance against apoptosis triggered by doxorubicin, durable in vivo tumor growth repression was observed after repeated injections of the nanoparticles containing doxorubicin followed by the nanoparticles containing the Bcl-2 siRNA." (PMID 28887666, 2017).
tumor (continued). "Besides, there were no significant changes in Bcl-2, BAX and Caspase-3 expression in tumor tissue from LNPS@Scrambled Bcl-2 treated tumor-bearing mice as compared with what were from normal saline treated tumor-bearing mice." (PMID 28514759, 2017). "Since NR4A1 plays a role to induce apoptosis through inhibiting Bcl-2, the tumor suppressor role may be partially attributed to its function to mediating apoptosis." (PMID 28903348, 2017). "Tumor-derived S1P triggers S1PRs on macrophages and reprograms their phenotype towards tumor supportive, by inducing antiapoptotic signaling cascades to stabilize the antiapoptotic proteins Bcl-2 and Bcl-XL." (PMID 28804221, 2017). "However, the combination treatment with both MCL-1 and BCL-2 inhibitors is capable of eliminating MICs which is needed to hinder relapse potential and block tumor regeneration." (PMID 27086916, 2017). "Overexpression of HER2 commonly causes the resistance of apoptosis by increasing anti-apoptotic proteins (e.g., Bcl-2, Bcl-X/L, Mcl-1, and survivin) and decreasing the proapoptotic protein Bim and, thus, contributes to tumor progression and contributes to the resistance to chemotherapy." (PMID 28335434, 2017). "Furthermore, HuR silencing increased the Bax/Bcl-2 ratio and caspase-3 activity, supporting the inhibition in carcinogenesis and tumor suppression." (PMID 28968471, 2017). "Thus inhibiting prosurvival BCL2 proteins is an attractive strategy to combine with ERK1/2 pathway inhibition to promote tumour cell death." (PMID 28548464, 2017). "A recent study proved that miR-195 had low expression rates in TSCC tumor samples, providing evidence that it might act as a tumor suppressor in this cancer type, by inhibiting Cyclin D1 and Bcl-2 expression." (PMID 29206174, 2017). "Suppression of tumor growth upon bortezomib monotherapy might result from the reduced expression of anti-apoptotic BCL-2, as has been previously shown in vitro for SCLC cells." (PMID 29228593, 2017). "ABT-199 can specially target Bcl-2 on tumor cells and induces B-lymphoma cell apoptosis." (PMID 28637496, 2017). "Moreover, upregulated protein expression of Bcl-2 contributes to the survival of tumor cells treated with either etoposide or doxorubicin (Dox)." (PMID 29113343, 2017). "To correlate cfDNA fragmentation with the events of necrosis and apoptosis, we performed IHC analysis of the Bcl-2 anti-apoptotic protein and the Bax and Bad pro-apoptotic proteins, and we precisely measured the percentage of the necrotic tumor area in each mammary sample." (PMID 28081183, 2017). "Additionally, an increased level of pro-apoptotic Bax and a decreased level of anti-apoptotic Bcl-2 protein were obviously found in the tumor tissue lysates from chaetocin-treated mice." (PMID 28419143, 2017). "However, tumor growth was dramatically hindered by LNPS@siBcl-2 as compared with LNPS@Scrambled Bcl-2." (PMID 28514759, 2017). "Bcl-2, which is overexpressed in most RCCs, contributes to tumor development and progression." (PMID 28464919, 2017). "Tumor suppressive miRNAs mediate the degradation or post-transcriptional inhibition of transcripts encoding oncogenes and can target ZEB1/2, HMGB2, Bcl2 and HIF-1α, which contribute to the increased proliferation, invasion, and EMT and reduce the apoptosis of cancer cells." (PMID 28085956, 2017). "Indeed, a selective decrease in Bax/Bcl‐2 expression represents a common mechanism of drug resistance in tumor cells." (PMID 28453190, 2017).
tumor (continued). "WWOX protein might interact with several molecules that are associated with tumor progression and angiogenesis, including RUNX2, bcl-2, P73, c-Jun, and Dvl-2." (PMID 28977834, 2017). "Inhibition of Bcl-2 and/or Bcl-xL has been shown to induce spontaneous apoptosis of tumor cells." (PMID 29029479, 2017). "In complementary work, a tumor cell line that was selected for resistance to immunotherapy upregulated AKT compared with sensitive wild-type cells, and this was associated with increased levels of BIRC2 and BIRC3, BCL-2 and BCL-XL." (PMID 29163772, 2017). "Bcl‐2 protein is a potent tumor suppressor and an important player in apoptotic signaling." (PMID 28088836, 2017). "In various kinds of tumor cells, the expression of BCL-2 is upregulated." (PMID 28720118, 2017). "Furthermore, Cu(sal)(phen) inhibited TNBC tumor growth in a xenograft model and induced apoptosis through down-regulating expression of anti-apoptosis proteins Bcl-2, Bcl-xL and survivin both in vitro and in vivo." (PMID 28415735, 2017). "Bcl-2 overexpression results in the inhibition of tumor cell apoptosis." (PMID 29113343, 2017). "In a variety of tumor cells, Bcl-2 and Bcl-xL are highly expressed to evade apoptosis." (PMID 29029479, 2017). "In conclusion, in this study we demonstrate that inhibition of two master regulators of cell survival, MCL-1 and BCL-2 with clinical stage drugs, voruciclib and venetoclax respectively, can achieve synergistic anti-tumor efficacy in a subset of ABC DLBCL models." (PMID 29269870, 2017). "CMLD-2 decreased HuR mRNA and the mRNAs of HuR-regulated proteins (Bcl2 and p27) in tumor cells." (PMID 28855578, 2017). "Bcl-2 expression was effectively positively correlated also to tumor size." (PMID 28081183, 2017). "Furthermore, a decrease in the apoptotic protein such as Bax 47, 48 and an increase in the anti‐apoptotic protein including Bcl‐2 as well as Mcl‐1 47, 49, regulated by miR‐139‐5p, also participates in the tumour process." (PMID 28780773, 2017). "In addition, tumor size was positively correlated with Bcl-2 expression in luminal cells (r = 0.4; P<0.0001) and marginal significance was found for a negative correlation with Bax IRS scale in luminal cells (r = -0.2; P = 0.05)." (PMID 28081183, 2017). "However, in vivo tests showed that LJSP significantly inhibited the growth of the U14-implanted tumor and markedly induced the apoptosis of tumor tissue cells by modulating the Bax/Bcl-2 ratio, which plays a crucial role in apoptosis." (PMID 28878139, 2017). "AS1411 is a guanine quadruplex aptamer that can bind to nucleolin, blocking the activation of secondary targets including nuclear factor-κB (NF-κB) and B-cell lymphoma 2 (BCL-2), therefore sensitizing the tumor cells to chemotherapy and improving their tumor-killing effects." (PMID 26863567, 2016). "Moreover, evidence suggests that overexpression of Bcl-2 in tumor cells can result in their escape from cell apoptosis and resistance to anticancer drugs." (PMID 27529071, 2016). "Therefore, the mild tumor growth inhibition by free G3139 was probably due to G3139 CpG immune stimulation instead of antisense binding to Bcl-2 mRNA." (PMID 27034925, 2016). "Moreover, when Bcl-2-overexpressing tumor cells were injected into the footpad, leg muscle, or tail vein of mice, their pulmonary metastasis was enhanced compared with that in control tumor cells." (PMID 26621844, 2016). "Docetaxel plays a vital role in the regulation of Bcl-2 phosphorylation, which might through the action of kinases in tumor cells." (PMID 27340870, 2016).
tumor (continued). "The persistent low levels of ER activity, PR and Bcl‐2 that we observed in fulvestrant relapse samples and the ER phosphorylation and Bcl‐2 detectable at pretreatment in PD patients provide further evidence for functional ER in some fulvestrant resistant tumours." (PMID 26178788, 2016). "Thus, in tumour cells with high BCL-2 expression, targeting apoptosis by combined protocols of BCL-2 with IAP inhibitors can provide efficient anti-cancer treatments in a synergistic manner." (PMID 27520705, 2016). "In addition, we observed that the downregulation of L3 expression along with increasing Bcl-2/Bax ratio correlated with increasing tumor grade." (PMID 27835895, 2016). "In addition, miR-181a was up-regulated in MDSC-D1, which promoted apoptosis by targeting Bcl-2 and suppressed tumor growth by targeting the MAPK-Snai2 pathway." (PMID 28536611, 2016). "Bcl-2 is a key protein in apoptosis and is highly expressed in multiple types of tumours." (PMID 27601167, 2016). "-Decrease tumor masses and anti-apoptotic protein, Bcl-2, and β-catenin." (PMID 26840292, 2016). "This could be due to the synergistic inhibitory effect of PTX and Bcl-2 siRNA on the tumor proliferation." (PMID 27786239, 2016). "This is in agreement with our previous results, which demonstrated that miR-143 overexpression reduces Bcl-2 expression in vitro, and reduces colon cancer tumor xenograft growth displaying higher levels of tumor cell apoptosis with decreased steady-state levels of Bcl-2." (PMID 26824186, 2016). "In summary, present study investigated the simultaneous delivery of siRNA and chemotherapeutic drug by pH-sensitive liposomal delivery system demonstrating the potential of co-delivery of PTX and Bcl-2 siRNA to enhance the chemotherapeutic efficacy in tumor cell line." (PMID 27786239, 2016). "Suppressing the expression of GLI could inhibit the overexpression of Bcl-2 and the proliferation of tumour cells, simultaneously promoting apoptosis." (PMID 27601167, 2016). "In tumour tissues, Bcl‐2 expression in the nucleus is correlated with poor prognosis." (PMID 27027258, 2016). "BCL-2 was the first anti-apoptotic gene discovered with clear implications in tumour biology." (PMID 27399772, 2016). "Similarly, lipo-Bcl-2 siRNA injection alone was unable to reduce the tumor volume to a considerable extent." (PMID 27786239, 2016). "To assess whether the recurrence of tumor was due to an acquired mechanism of Bcl-2 antagonist resistance, such as an adaptation to Mcl-1 dependence, we retreated one mouse and assessed the other tumor for changes in Bim binding by co-IP." (PMID 26874859, 2016). "Moreover, tumor cell-intrinsic RelB was responsible for the abundant levels of c-Myc, cyclin D1, Bcl-2 and Bcl-xL, which are key regulators of cell cycle transition, apoptosis and proliferation in EEC." (PMID 27711077, 2016). "Tumor cells within each core were assessed for Bcl-2 protein levels." (PMID 27120789, 2016). "The researchers found that the Aloe vera and honey mixture increased the expression of the proapototic protein Bax, especially on day 20, while inhibiting expression of the antiapoptotic protein Bcl-2, especially in the early stages of the tumour development (day 7 and day 14)." (PMID 28933410, 2016). "Conceivably, BCL2 might represent a HH/GLI target pivotal for tumor growth only in specific cell lines." (PMID 26775700, 2016).
tumor (continued). "Furthermore, the anti-apoptotic genes Bcl-2, Bcl-xL and Mcl-1 were all independently prognostic of favourable outcome, which argues against a simple anti-apoptotic/tumor-promoting role for these genes." (PMID 27120789, 2016). "Thus, high expression levels of anti-apoptotic proteins Bcl-2 and Bcl-xL have been reported to correlate with cisplatin resistance and tumor recurrence in different cancers including non-small cell lung cancer (NSCLC), head and neck, ovarian, and breast." (PMID 27019364, 2016). "Furthermore, the ex vivo tumor sections analysis showed that the protein levels of Bax, Bcl-2, GRP-94, and calpain I increased (~1.2 to 3.01 fold) or decreased (~0.55 to 0.04 fold) significantly in the ACDB-stimulated group than the control group." (PMID 27835579, 2016). "Together with the accumulation of salmonella in tumor and the inhibition of angiogenesis by HM-3, more tumor cells went through cell apoptosis with increased expression of Bax, cleaved Caspase 3 and decreased expression of Bcl2." (PMID 27371094, 2016). "Since clinical data link expression levels of anti-apoptotic factor Bcl2 with cisplatin resistance and recurrent disease, we compared the expression of La and Bcl2 protein in tissue lysates obtained from normal tongue and tumor tissues of HNSCC patients." (PMID 27105491, 2016). "Tumours with weakly detectable T3‐T4 increases in pEGFRm also showed modest HER2m increases (p = 0.027) and Spearman's analysis revealed direct associations at T4 between EGFR activity and pER (p = 0.006), Bcl‐2 (p = 0.055) and Ki67 (p = 0.047)." (PMID 26178788, 2016). "The enhanced ability of delivering PTX/Bcl-2 at the tumor microenvironment potentially may support the low-dose systemic chemotherapy with low side effects." (PMID 27786239, 2016). "Therefore, when cyclopamine blocks SHH signaling to decrease Gli-1 mRNA expression, a corresponding decrease in Bcl-2 mRNA can occur, which can promote apoptosis of tumor cells." (PMID 26716648, 2016). "However, low-dose CTX with oral MAA significantly depressed tumor growth, and this was accompanied by an increased Bax/Bcl-2 ratio, increased caspase 3 expression, and increased apoptosis." (PMID 27043621, 2016). "Importantly, the expression of JMJD3, IRF4 and BCL2 in tumor tissues derived from JMJD3 siRNA-treated mice were dramatically decreased when compared to tumors from the control animals." (PMID 27102442, 2016). "Our previous study reported miR-206 could also target 3′-UTR of MET and BCL2, and activate apoptosis, inhibit tumor cell proliferation, migration and colony formation in NSCLC cell lines (A549 and SK-MES-1)." (PMID 26909600, 2016). "Furthermore, TM increased the levels of cleaved poly-ADP-ribose polymerase (PARP), Bad, and Bax and reduced the expressions of B-cell lymphoma 2 (Bcl-2) in treated cells and tumor tissues." (PMID 28018916, 2016). "Post-hoc non-parametric Mann-Whitney test showed that normal thyroid tissue was significantly different (p<0.05) from every tumor type for each marker, except for bcl-2 where significant difference was found only with encapsulated FVPTC and with metastatic PTC." (PMID 26863116, 2016). "Our data showing the concomitant loss of pHH3+ cells and gain in CC3+ cells in Abraxane/ABT-263 co-microinjected regions is consistent with the proposal that inhibition of BCL2/BCLxl drives cells towards the apoptotic fate ultimately leading to tumor regression." (PMID 27359113, 2016). "Because miR-34a expression suppressed expression of Bcl-2 and enhanced release of cytochrome c from the mitochondrial endomembrane, miR-34a may significantly amplify the anti-tumor effect of Smac by enhancing Smac-induced activation of the Caspase pathway." (PMID 27552933, 2016). "To assess if the pattern of tumor gene expression in the parental cancer cells could be returned to a comparatively benign states, we analysed the expression of two tumor suppressors (p19ARFand p16INK4a) and two oncogenes (Bcl2 and C-fos)." (PMID 27468690, 2016).